STAT3 (signal transducer and activator of transcription 3)
Diseases named in the same sentence as STAT3 in open-access papers (continued):
Sharing a sentence is not in itself a finding about the gene and the disease.
tumor (continued). "IL‐6 secreted from CRP‐stimulated HMDMs also induced STAT3 activation in both HMDMs and tumor cells." (PMID 39564003, 2024). "STAT3 also plays a role in exacerbating cancer cachexia through the promotion of metastasis, immune suppression, and tumor growth." (PMID 38807976, 2024). "Inflammation and hypoxia, essential conditions for tumor growth, accelerate tumor initiation and proliferation by promoting genomic instability and activating key signaling pathways such as STAT3 and NF-κB." (PMID 38673727, 2024). "Consistent with earlier research, these findings show that IL-6 regulates tumor formation and glucose metabolism via the IL-6R/STAT3 axis." (PMID 39060229, 2024). "STAT3 signalling is important for driving tumour growth, migration, angiogenesis and inflammatory crosstalk with immune cells during carcinogenesis." (PMID 39187514, 2024). "MiRNAs act as tumor suppressors by directly targeting and inhibiting STAT3 expression, hindering tumorigenesis." (PMID 38185635, 2024). "The immunosuppressive role of STAT3 in tumor cells, T cells, B cells, myeloid cells, and dendritic cells (DCs) has been documented extensively." (PMID 39618825, 2024). "In tumor biology, aberrantly activated STAT3 emerges as a pivotal oncogenic factor, promoting cell proliferation, survival, invasion, and metastasis." (PMID 39695099, 2024). "IL-6 was reported to skew T-cell differentiation toward Th2 by STAT3 signaling pathway, resulting in the suppression of anti-tumor response." (PMID 39963655, 2024). "The overexpression of miR-19a was shown to downregulate PTEN mRNA expression, promote cell viability and EMT in CRC cells, and increase tumor growth and metastasis in nude mice models through STAT3/miR-19a/PTEN axis." (PMID 38185635, 2024). "While the effect of STAT3 activation in tumor cells on the inflammatory infiltrate is well characterized, the effects on the tumor-stroma is less well-studied." (PMID 38424636, 2024). "More importantly, the influence of TBL1XR1 on tumor development of osteosarcoma were mediated by stimulation of the STAT3 signaling pathway." (PMID 38347836, 2024). "Here the authors use human samples and mice tumour models to implicate serum amyloid A and STAT3 signalling involvement in the resistance to anti-PD1 immunotherapy in HCC." (PMID 38409200, 2024). "STAT3, a key transcription factor involved in tumorigenesis and a convergence point for multiple oncogenic pathways, plays a crucial role in tumor initiation and progression." (PMID 38402166, 2024). "Nobiletin inhibits the expression of PD-L1 by EGFR/JAK2/STAT3 signaling pathway, thereby enhancing anti-tumor immunity." (PMID 38361933, 2024). "Qu released by QFN can decrease the expression of PD-L1 in tumor cells by inhibiting the phosphorylation of JAK2 and STAT3, thereby enhancing anti-tumor immunity." (PMID 39712006, 2024). "Western blot analysis indicated that caspase-3/EndoG knockout significantly reduced the level of phosphorylated STAT3 at Y705 (pSTAT3) in mPOR-transformed cells as well as in tumor samples from Casp3WT;Pymt and Casp3KO;Pymt mice." (PMID 38977663, 2024). "STAT3-induced overexpression of tumor-promoting miR-216a downregulates tumor suppressor gene PTEN (phosphatase and tensin homolog), which regulates the PI3K/AKT (Phosphatidylinositol 3-kinase and Protein Kinase B) oncogenic pathway." (PMID 39766086, 2024). "Treatment of CEP-701, a TKI, resistant-MV4-11 cell line with azacitidine, resulted in re-expression of SHP-1, a tumor suppressor gene and negative regulator of STAT3, leading to suppression of STAT3 and induction of apoptosis." (PMID 38696033, 2024). "Conversely, PTEN-deficient tumor cells have constitutive activation of AKT, and STAT3 is inactive in these cells." (PMID 38339245, 2024). "Hypoxic properties in TME catalyse the binding of PD‐L1 and p‐STAT3 in the nucleus of tumour cells, leading to nuclear translocation and increasing GSDMC expression." (PMID 38652105, 2024).
tumor (continued). "The IL-6/JAK/STAT3 signaling directly promotes tumor progression, severely hampering antitumor immunity." (PMID 38274367, 2024). "For example, the H2S donor GYY4137 has been shown to inhibit tumor angiogenesis by disrupting the STAT3 signaling pathway in hepatocellular carcinoma, and another H2S donor, diallyl sulfide (DAS), has been confirmed in mouse models." (PMID 39710789, 2024). "STAT3, often excessively activated in cancer, plays a crucial role in the signaling pathways of tumor cells." (PMID 39056720, 2024). "For tumor cells, IL‐6 can drive the activation of STAT3, which can promote tumor initiation and progression, resist apoptosis and promote metastasis." (PMID 39235042, 2024). "M1 macrophages promote the tumor microenvironment by producing pro-tumor cytokines and have a proliferative effect on colon cells through the NF-κB and STAT3 pathways." (PMID 38516408, 2024). "The JAK2/p-STAT3 pathway is an important pathway involved in the endogenous expression of PD-L1 (in tumor and immune cells) that promotes cancer progression." (PMID 38872221, 2024). "Constitutive activation of STAT3 contributes to tumor development and metastasis, making it a promising target for cancer therapy." (PMID 39195486, 2024). "Here, we provide evidence that bazedoxifene inhibits tumour growth via direct interaction with the gp130 receptor to suppress IL-6 and IL-11-mediated STAT3 signalling." (PMID 38600086, 2024). "MDSCs secrete IL-6 by activating the signal transducer and activator of transcription 3 (STAT3) signaling pathway, promoting tumor growth and invasion." (PMID 38523646, 2024). "Patients with high STAT3 expression exhibited advanced tumor clinicopathological parameters and worse survival." (PMID 38273295, 2024). "Immunosuppressive cytokines (such as IL-10, PD-L1, and TGF-β) activate the STAT3 signaling pathway, leading to tumor immune suppression and epithelial–mesenchymal transition." (PMID 38920657, 2024). "In brief, these results demonstrated that YY002 selectivelysuppressed the proliferation of tumor cells by targeting STAT3." (PMID 38559310, 2024). "It is found that STAT3 is abnormally activated in GBM, and inhibiting STAT3 signaling can effectively suppress tumor progression." (PMID 39153914, 2024). "One day after the third injection of PBS or CpG-Stat3 siRNA, mice were euthanized, and the tumor tissues were harvested to assess Stat3 mRNA expression by real-time qPCR." (PMID 39618825, 2024). "Previous studies revealed that the supernatant of tumor cells from specific cell lines promotes the activation of signal transducer and activator of transcription 3 (STAT3), a process that drives the migration of macrophages toward the M2 phenotype." (PMID 39290697, 2024). "STAT3 is a pro-inflammatory transcription factor that promotes oncogenesis by enhancing tumour survival, motility, and cell proliferation." (PMID 39070657, 2024). "LNRRIL6 upregulation promotes CRC cell survival, proliferation, and in vitro tumor growth through the IL-6/STAT3 axis." (PMID 38185635, 2024). "We also identified well-known transcription factors, such as JUN and STAT3, which were found to be targeted and regulated by m6A during tumor progression and tumor immunity." (PMID 38970366, 2024). "METTL3 enhances ribosomal translation efficiency through the METTL3/m6A/JAK1/STAT3 axis and facilitates tumor immune evasion." (PMID 38879589, 2024). "Studies have shown that the downstream product of the cGAS-STING pathway, IL-6, can activate the STAT3 signaling pathway in tumors, thereby promoting tumor growth." (PMID 38523155, 2024).
tumor (continued). "Subsequently, the deficiency of miR-338-5p in hypoxic cancer cells moderated the decrease in IL-6 expression and reactivated the anti-apoptotic STAT3/Bcl2 signaling pathway, thus impeding tumor cell death and improving the drug resistance of tumor cells." (PMID 37588219, 2024). "Conversely, suppressing PBX1 enhances the radiosensitivity of esophageal squamous cell carcinoma by targeting STAT3, inhibiting tumor cell proliferation and tumor growth." (PMID 39129784, 2024). "NF-κB and STAT3 cooperatively promote tumor development through functional interactions, inducing pro-tumor genes, including genes that generate anti-apoptotic chemokines and immunosuppressive cytokines." (PMID 38183097, 2024). "Recently, the crosstalk between lipid metabolism and tumorigenesis mediated by STAT3 are observed through the cytokines, hormones and adipokines, which paracrine or endocrine secreted by the adipose tissues around the tumor cells." (PMID 38245798, 2024). "Second, miRNAs can target components of the STAT3 signaling pathway to alter STAT3 expression, ultimately regulating the biological phenotype of tumor cells." (PMID 38172648, 2024). "Research indicates that inhibiting circSEPT9 can induce tumor cell apoptosis and inhibit tumor growth by downregulating the LIF/STAT3 signaling pathway." (PMID 39584047, 2024). "It has been demonstrated that resveratrol can reach sub-micromolar concentrations in the brain parenchyma when administered through standard routes, where it inhibits tumor growth through STAT-3-dependent mechanisms." (PMID 39720087, 2024). "It is worth mentioning that besides an IL‐6/JAK2/STAT3 axis‐dependent induction of a macrophage‐tumor cell crosstalk our study uncovered an EV‐mediated crosstalk between tumor cells and macrophages." (PMID 38031260, 2024). "Altered expression of these ILs regulates the expression of STAT3, ultimately affecting the proliferation, migration, and invasion of tumor cells." (PMID 38172648, 2024). "For instance, the incorporation of MiR-3591-3p into glioma exosomes promotes M2-type polarization of macrophages through the JAK2/PI3K/Akt/mTOR and STAT3 pathways, thereby enhancing tumor invasion and migration." (PMID 38195554, 2024). "Analysis of MyD88/TRIF knockout mice with nuclear ATF6 expression in intestinal epithelial cells (nATF6IEC) showed that tumor development was dependent on the activation of STAT3 through MyD88/TRIF signaling." (PMID 38903520, 2024). "In vitro studies have revealed that S3I-201 significantly diminishes the TNBC cell viability and inhibits tumor growth by reducing STAT3 phosphorylation." (PMID 38699644, 2024). "[18F]FBNAF exhibited high stability in vitro and in vivo, and radioactivity accumulated in tumor tissues expressing STAT3 with an increasing tumor/blood ratio over time, peaking at 2.6 ± 0.8 at 120 min after injection in tumor-bearing mice." (PMID 38834900, 2024). "As such, the influence of STAT3 on the TME favors a pro-tumor environment that promotes immune escape." (PMID 38464736, 2024). "STAT3, which contains a tandem splice site, can produce specific isoforms, STAT3α and STAT3β with distinct cellular roles of tumor promoters and tumor suppressors." (PMID 38535990, 2024). "YY002 potently inhibited STAT3-dependent tumorcell growth in vitro and achieved potent suppressionof tumor growth and metastasis in vivo." (PMID 38559310, 2024). "Tumor-suppressive lncRNA MEG3 regulates STAT3-driven CRC cell stemness by sequestering and downregulating miR-708." (PMID 38185635, 2024). "This led to the concept that in tumor cells, IL-6 activates Stat3, which in turn leads to the release of IL-6." (PMID 39000275, 2024).
tumor (continued). "STAT3 phosphorylation is also enhanced in the tumor microenvironment, creating an immunosuppressive environment." (PMID 38834900, 2024). "In view of our findings indicating the activation of STAT3 signaling pathway through the degradation of SUZ12 and EZH2 mediated by SUMOylated HSPA9, we investigated the role of STAT3 in MUL1-induced tumor inhibition effects." (PMID 39113711, 2024). "We found that STAT3 KD reduced tumor growth and lung metastasis compared with STAT3 control in SMARCB1 KO BLCA tumors." (PMID 38355560, 2024). "For example, the upregulation of FGF signaling is found to be a critical mechanism in which the Janus kinase 2/signal transducer and activator of transcription 3 (JAK2/STAT3) pathway mediates tumor angiogenesis in NSCLC." (PMID 39796710, 2024). "By suppressing CCR7, miR-21-5p reduces STAT3 signaling, highlighting a potential therapeutic target to curb tumor growth." (PMID 39590345, 2024). "Phosphorylation of STAT1 impedes tumor growth, whereas STAT3 and STAT5 play roles in the initiation and development of tumors." (PMID 38338162, 2024). "The IL‐6/STAT3 pathway involves key proteins like Bcl‐2 and Bax, crucial for tumour cell apoptosis and Cyclin D1 and CDK‐4, which contribute to tumour cell proliferation." (PMID 39495702, 2024). "Elevated levels of IL-6, phosphorylated JAK2, and phosphorylated STAT3 are consistently observed across these malignancies, contributing to tumor growth, metastasis, and resistance to apoptosis." (PMID 39125732, 2024). "Inflammatory factors, particularly IL-6, can activate the STAT3/NF-κB pathway in both stromal and tumor cells." (PMID 39309424, 2024). "STAT3 knockout blocked the secretion of VEGF, IL‐6, and IL‐10, causing an imbalance in the tumor ecosystem." (PMID 38923275, 2024). "Andrographolide (a terpenoid) inhibits NSCLC tumor growth by inhibiting the phosphorylation of STAT3 and p62 accumulation, regulating selective autophagic degradation of PD-L1, and increasing the infiltration and function of CD8+ T cells." (PMID 38792234, 2024). "For example, heat shock protein 110 can directly bind to STAT3 and facilitate its phosphorylation, contributing to tumor growth in colon cancer patient samples." (PMID 38611065, 2024). "Further data show that breast cancer cells and CD169 macrophages show two-way interaction, which plays a key role in tumor progression by activating JAK2/STAT3 signaling pathway in macrophages." (PMID 38693304, 2024). "In conclusion, SAL exerted anti-tumor effects by interfering with the malignant biological progression of OC cells by inhibiting STAT3/c-Myc pathway-mediated glycolysis." (PMID 39097833, 2024). "JAK2/STAT3 is a classical IL-6 signaling pathway that can promote inflammation and tumor progression." (PMID 38424624, 2024). "STAT3 plays a pivotal role in various tumor-related processes, including cell proliferation, survival, angiogenesis, and invasion." (PMID 39493763, 2024). "Circ‐0009092 regulates STAT3 modification and reduces CCL2 expression by targeting the miR‐665/NLK signaling axis, which inhibits tumor‐associated macrophage aggregation and slows down the EMT progression of tumor." (PMID 39584047, 2024). "Exosomes containing FGD5-AS1: It was demonstrated that when these EVs are co-cultured with M2 macrophages, they promote tumor progression via the activation of STAT3/NF-κB pathway, which worsens the prognosis in PDAC patients." (PMID 38542378, 2024). "Mesenchymal stem cells activate STAT3 in OS cells through secretion of IL-6, thereby increasing tumor growth and metastasis and decreasing apoptosis." (PMID 39199574, 2024). "Mechanistic studies showed that PPA inhibited the NF-κB and STAT3 signaling pathways in tumor cells." (PMID 39085255, 2024). "Conversely, activation of STAT3 and STAT6 by IL-4 and IL-13 predominantly leads to polarization of macrophages towards the M2 phenotype, associated with immune suppression and tumor progression." (PMID 38745331, 2024).
tumor (continued). "Patient-derived xenografts and genetically engineered mouse models have yielded contrasting findings regarding the role of STAT3 in cancer development that range from tumor-promoting to tumor-suppressive, suggesting a high degree of tissue specificity." (PMID 38573819, 2024). "STAT3 is an important transcription factor on both tumor growth and maintenance of stemness of cancer cell." (PMID 38977663, 2024). "In agreement with previous findings, advanced metastatic tumours derived from mice expressing STAT3 in HStCs (STAT3WT, Cre-) were rich in YM1+ macrophages." (PMID 38678021, 2024). "IL6 can reverse the SLC7A11 knockout effect through the JAK2/STAT3 pathway, inhibit ferroptosis and promote tumor resistance." (PMID 39544949, 2024). "IL-17 has also been found to promote B16 (melanoma) tumor growth by inducing IL-6 expression and activating Stat3 signaling." (PMID 39906741, 2024). "PI3Kβ inactivation in the PTEN- null setting led to reduced STAT3 signaling and increased the expression of immune stimulatory molecules, thereby promoting anti-tumor immune responses." (PMID 39206155, 2024). "Irrespective of the prevailing combinations of mutations in KPP or KPT mice, we discover a gatekeeper role for tumor-cell-intrinsic STAT3 signaling that provides attractive therapeutic targets, including interference with the activity of upstream cytokines." (PMID 39128004, 2024). "The mechanism by which CPT exhibited its anti-tumor impact involved focusing on the STAT3/SIRT3/HIF-1α signaling cascade both in vitro and in vivo." (PMID 38397437, 2024). "For instance, astragaloside IV promotes the infiltration and activation of CD8+ T cells, reduces regulatory T cell (Treg) infiltration in tumors, and inhibits tumor angiogenesis by regulating multiple signaling pathways, such as STAT3 and NF-κB11,12." (PMID 39085255, 2024). "Mechanistically, IL-6 exerts its effects on tumor initiation, progression, angiogenesis, immune modulation, and metastasis primarily via the STAT3 pathway." (PMID 38689325, 2024). "As a nexus of numerous carcinogenic signaling pathways, STAT3 centrally regulates the anti-tumor immune response." (PMID 39494324, 2024). "Downregulation of STAT3 signaling by blocking β-AR signaling (a clinically relevant target), or disruption of STAT3-mediated itaconate result in an improved anti-tumor effect of doxorubicin." (PMID 38555305, 2024). "STAT3 plays a critical role in the development of apoptosis abnormality in tumor cell lines, which promotes an apoptosis-resistant environment via the activation of survivin, NFAF and Bcl-2." (PMID 38733520, 2024). "Mechanistically, the alteration of CAFs-derived AKT2/CCTα axis and its-activated intratumoral JAK2/STAT3 pathway induces the resistance of FAK inhibitor in tumor treatment." (PMID 38280862, 2024). "The lncRNA HOST2 (human ovarian cancer-specific transcript 2) promotes proliferation and migration by competing with let-7b to upregulate STAT3, a potential target in both tumor cells and immune infiltrates, as discussed in the previous section." (PMID 39272915, 2024). "JAK2/STAT3 signaling contributes to the development of a tumour inflammatory microenvironment that correlates with the occurrence and development of many human cancers." (PMID 38305998, 2024). "The promotion of migration, invasion, metastasis, angiogenesis and immune escape of tumors characterizes the tumor-promoting effect of STAT-3 phosphorylation." (PMID 39557919, 2024). "Immunotherapy is a promising approach, exemplified by targeting JAK/STAT3 signaling, which can inhibit tumor growth and enhance antitumor immune responses." (PMID 38817669, 2024). "After the miRNA is upregulated, it can induce the production of IL-6 to form a STAT3/miRNA/IL-6 loop, or can regulate the expression of downstream target genes, thereby promoting tumor cell growth and accelerating cancer progression." (PMID 38172648, 2024).